IL6 (interleukin 6)
Diseases named in the same sentence as IL6 in open-access papers (continued):
Sharing a sentence is not in itself a finding about the gene and the disease.
prostate carcinoma (continued). "In the literature, many experimental and clinical data highlight an important role for interleukin 6 (IL-6) in prostate cancer development and progression." (PMID 34576340, 2021). "Consistently, we found increased IL-6 in prostate cancer tissues of patients compared with normal prostate tissues." (PMID 32971847, 2020). "IL-6, a mediator of chronic inflammation, induces the progression of prostate cancer, and influences the polarization of M2 macrophages, which are the main tumor-associated macrophages." (PMID 32196489, 2020). "Elevated serum levels of IL-6, IL-8, TNF-α, and CCL2 are associated with accelerated progression and poor prognosis in prostate cancer patients." (PMID 33076397, 2020). "The anti-IL-6 antibody siltuximab (CNTO 328) has been shown to delay development of castrate resistance in prostate cancer in vitro and in vivo." (PMID 35582225, 2020). "Our data on only little induction of IL1β and IL6 in myeloid cells by prostate cancer cell-derived supernatants are in line with previous findings." (PMID 32316245, 2020). "In human prostate cancer cells, the role of IL-6 in promotion of metastasis has been extensively described." (PMID 32585812, 2020). "The study was able to promote new perceptions on the function of IL-6 in AR activation in prostate cancer cells and as inhibited by resveratrol." (PMID 32961987, 2020). "Other therapeutics that target inflammation that exacerbate COVID19 infection are currently being investigated, such as IL-6 inhibitors, which have also been studied for potential treatment of prostate cancer." (PMID 33076397, 2020). "The increase in proliferation and migration in TCM-stimulated prostate cancer cells is due to the effects of inflammatory cytokines such as IL-6 and CXCL8 in TCM, which is consistent with our previous study." (PMID 32196489, 2020). "Research shows that hormone resistant prostate cancer cells have increased IL-6 expression and activated STAT3." (PMID 32326381, 2020). "Consistent with our findings, high levels of IL-6 were detected in prostate cancer tissues and sera of patients with advanced prostate cancer." (PMID 32971847, 2020). "The activation of IL-6 signaling can drive growth, proliferation and migration of prostate cancer cells." (PMID 33076397, 2020). "Stimulation of muscle contraction during PRT releases myokines that lower systemic inflammation, with 4–8 weeks of PRT reducing serum IL-6 and TNFα in prostate cancer patients." (PMID 32056047, 2020). "LNCaP prostate cancer cells have reduced sensitivity to androgen depletion, when there is constitutive expression of IL-6." (PMID 33076397, 2020). "The expression of S100P in the colon is mediated by prostaglandin E2 (PGE2)–prostaglandin E receptor 4 (PTGER4) signaling, in prostate cancer by IL-6, and in breast and cervical by glucocorticoids." (PMID 33005177, 2020). "We further assessed the levels of IL-6 in CAF-conditioned media from different prostate cancer patients by ELISA and detected IL-6 at concentrations between 0.25 and 0.60 ng/mL in the CAF-conditioned media, while LNCaP did not produce any detectable IL-6." (PMID 32528731, 2020). "Given the complexity of IL-6 interactions in prostate cancer, a customized approach is required to identify patients who will benefit from anti-IL-6 therapy in conjunction with standard treatments." (PMID 35582225, 2020). "The study revealed for the first time that stimulating human prostatic carcinoma cell line- fast growing colony (LNCaP-FGC) cells with IL-6 clearly induced the AR transcriptional activity while resveratrol reduced IL-6-induced AR activity." (PMID 32961987, 2020).
prostate carcinoma (continued). "Inhibition of IL-6 with siltuximab suppressed castration-resistant progression in androgen-dependent prostate cancer xenograft model mice." (PMID 32824865, 2020). "Human and murine prostate cancer models have exhibited varying effects of IL-6 and/or STAT3 on tumor cell growth." (PMID 35582225, 2020). "The IL-6/Janus kinase (JAK)/STAT3 pathway is aberrantly hyperactivated in many types of cancer, including prostate cancer, and such hyperactivation is generally associated with a poor prognosis." (PMID 32824865, 2020). "Immunohistochemical analysis demonstrated that the expression of IL-6 is increased in prostate cancer induced by intraprostatic injection of LNCaP cells stably transfected with SFMBT2 shRNA." (PMID 32971847, 2020). "Challenging the present dogma of IL-6 role in promotion of prostate cancer metastasis is a recent study." (PMID 32585812, 2020). "Further, in vitro studies have demonstrated that IL-6 treatment promotes motility, migration, and decreases the adhesion of prostate cancer cells." (PMID 33076397, 2020). "The results of prospective, longitudinal, phase II study showed that the serum levels of IL-6 tended to increase in patients with early stage prostate cancer during external beam radiotherapy." (PMID 33149212, 2020). "The first is that all the papers in the literature describing the effect of IL6 on prostate cancer cells used LNCaP cells)." (PMID 32802517, 2020). "Prostate cancer cells and surrounding prostate stroma cells express high levels of inflammatory cytokines including interleukins IL-1, IL-6, and IL-8 in order to promote prostate tumor proliferation and survival." (PMID 33076397, 2020). "Several studies have reported IL-6 as a prognostic factor in prostate cancer, with elevated serum levels found in patients with metastatic disease." (PMID 32585812, 2020). "While IL-6 derived from macrophages and adipocytes has pro-inflammatory effects, muscle-derived IL-6 can counteract TNF-α, which as previously discussed, is associated with significantly worse outcomes in men with prostate cancer." (PMID 32056047, 2020). "Knockdown of E2F1 in prostate cancer cell line DU145 results in the reduced expression of cytokines including Il-6." (PMID 33291686, 2020). "It has been reported that STAT3-mediated Twist transcription is involved in IL-6/Hsp27-mediated EMT via STAT3 targeting of the Twist promoter in prostate cancer." (PMID 32315283, 2020). "IL-6 signaling has also been implicated as a potential inflammatory driver of therapeutic resistance in prostate cancer, with increased circulating IL-6 in patients with resistant disease." (PMID 33076397, 2020). "In turn, IL-6 from infiltrated preadipocytes and TAMs further promotes migration and invasion of prostate cancer cells." (PMID 32971847, 2020). "Our recent study reported that IL-6 of prostate cells produced by T. vaginalis infection induces the proliferation of prostate epithelial cell as well as prostate cancer cells." (PMID 32196489, 2020). "Of note, C188‐9 treatment significantly enhanced NDV/FMW‐induced inhibition of growth in prostate cancer cells whereas pretreatment with IL‐6 gave the opposite effects." (PMID 32100392, 2020). "Human prostate carcinoma-associated fibroblasts and prostate cancer cells orchestrate and enhance TAM and MDSC recruitment to prostate tumors as well as M2-like TAM differentiation by the chemokines CCL2, CXCL12, and IL-6 during cancer progression." (PMID 32824865, 2020). "Recently, Culig and Puhr have elegantly reviewed the role and regulation of IL-6 in prostate cancer." (PMID 32039001, 2019). "We found that rTRAIL and sTRAIL induced CXCL5/ENA-78 and IL-6 expression in TRAIL-resistant prostate cancer cells." (PMID 31010082, 2019). "Several signaling pathways downstream of IL-6 orchestrate angiogenesis and NE phenotype in prostate cancer." (PMID 32039001, 2019).
prostate carcinoma (continued). "Immune cells, such as Tregs, Th17 cells, and macrophages, are also involved in prostate cancer progression while cytokines, such as IL-6 and RANKL, secreted by cells in the TME have been found to have a pleiotropic effect on prostate cancer cells." (PMID 31013716, 2019). "In immunocompetent mouse models, we showed that blockade of IL-6 in prostate cancer cells significantly attenuated IL-6 signaling, decreased the expression of CD44, and attenuated the immunosuppressive tumor microenvironment." (PMID 31315262, 2019). "We further examined the correlation between the levels of IL-6 and clinical characteristics of prostate cancer patients." (PMID 31315262, 2019). "One of these mechanisms is triggered by the cytokine IL-6, whose levels are considerably increased in prostate cancer." (PMID 31366128, 2019). "IL-6 is largely expressed in androgen-independent prostate cancer cell lines, and overexpression of IL-6 in LNCaP can lead to these cells being resistant to androgen deprivation therapy." (PMID 30646518, 2019). "Inflammatory cytokine interleukin 6 (IL-6) serves as a growth factor in prostate cancer cells and is elevated in serum as well as in cancer tissue of prostate cancer patients." (PMID 30791439, 2019). "HSP27 is also involved in the process of prostate cancer metastasis through the promotion of IL-6-mediated epithelial-to-mesenchymal transition (EMT), because reduced HSP27 expression decreases cell migration and invasion." (PMID 31861612, 2019). "IL-6 is commonly produced by a variety of cancer types including breast, lung, liver, and prostate cancer and elevated serum IL-6 is generally correlated with poor outcomes in cancer patients." (PMID 31174326, 2019). "In a murine model of xenograft prostate cancer, an anti-IL-6 monoclonal antibody was able to induce the inhibition of outgrowth of a patient-derived castrate-resistant tumor." (PMID 31366128, 2019). "We only know, from one study of prostate cancer, that IL-6 stimulation leads to HSP27 phosphorylation and correlates with the EMT, suggesting the phosphorylated form is required for STAT3 activation." (PMID 31861612, 2019). "IL-6 is a multifunctional cytokine known to participate in the malignant progression of prostate cancer." (PMID 31581708, 2019). "With the exception of targets above, interleukin-6 (IL-6) showed high expression in prostate cancer." (PMID 31552191, 2019). "The overexpression of IL-6 in prostate cancer cell line LNCaP was shown to significantly accelerate the growth of tumor through an increase in the expression of phosphorylated extracellular signal-regulated kinase (pERK)." (PMID 31252615, 2019). "Overexpression of IL6 is tightly related to many tumours including breast, liver, lung, and prostate cancers, and its amplification has been reported in human glioblastomas." (PMID 31041889, 2019). "Interleukin-6 (IL-6), a pluripotency cytokine, is involved in the malignant progression of prostate cancer, while N-myc downstream regulated 1 (NDRG1) is a tumor suppressor gene in numerous cancer cells, including prostate." (PMID 31581708, 2019). "Steiner demonstrated that the overexpression of IL-6 in prostate cancer resulted in a significant increase in cell proliferation through the upregulated expression of CDK2 and increased expression of pERK." (PMID 31252615, 2019). "Due to the fact that mouse IL-6, secreted by mouse macrophages and natural killer cells, is not able to activate the human IL-6R we examined the IL-6 expression in human prostate cancer cells after co-incubation with mouse IIR cells." (PMID 30134795, 2018). "The present study was aimed to investigate the potential role and related mechanisms of GCN5 in IL-6–treated prostate cancer (PCa) cell." (PMID 30333255, 2018).
prostate carcinoma (continued). "In fact, apart from CLU, also CEBPB and D seem to play a role in PC proliferation, as interleukin-6 (IL-6) treatment increases the expression of CEBP-D family member, inducing IL-6/STAT3-dependent growth arrest on prostate cancer cells in vitro." (PMID 29562723, 2018). "Exogenous IL-6 leads to the production and secretion of IL-6 and PEc from prostate cancer cells and tumors, by activating IL-6R and JAK2/STAT3 pathway." (PMID 30134795, 2018). "In prostate cancer, the altered miRNA profile of normal control fibroblasts treated with IL-6 resembled that of CAFs." (PMID 29347950, 2018). "Blocking of IL-6 using an anti-human IL-6 monoclonal antibody in prostate cancer cell lines treated with IL-6, inhibited the IGF-1Ec production." (PMID 30134795, 2018). "The GCN5 mRNA and protein expression levels in human prostate carcinoma cell lines after IL-6 treatment were investigated using RT-qPCR and Western blotting assay." (PMID 30333255, 2018). "Evidence obtained from prostate cancer biopsies suggests that human prostate tumors express IL-6 in many instances." (PMID 30134795, 2018). "In prostate cancer cell-based and xenograft models, IKKε promoted proliferation and tumor growth along with interleukin 6 (IL-6) expression in a manner dependent on the nuclear accumulation of the transcription factor C/EBPβ." (PMID 30223576, 2018). "Prostate cancer is mainly supplemented by numerous molecular vicissitudes, mostly an overexpression of serum interleukin-6 (IL-6)." (PMID 30545141, 2018). "Levels of SPRY2 and IL6 showed a significant inverse correlation in ADT‐treated prostate cancer patients with evidence of biochemical relapse (r = −0.427; P = 0.0261; n = 27; Fig EV4E)." (PMID 29540470, 2018). "It was determined that the media obtained from the co-culturing experiments was able to generate the IL-6 production in prostate cancer cells and this effect was abolished when the anti-IL-6R antibody was introduced into the media." (PMID 30134795, 2018). "Overall, androgen‐independent CWR22RV1 and DU145 prostate cancer cells showed higher levels of IL6 expression compared to hormone‐responsive LNCaP and CWR22Res cells (Fig EV4F)." (PMID 29540470, 2018). "Two of the most frequently studied cytokines and chemokines in relation to prostate cancer development and pathophysiology are Interleukin-6 (IL6) and C-X-C motif chemokine ligand 8 (CXCL8)." (PMID 30473726, 2018). "Treatment of the cancer cells (PC-3 and DU-145) with IL-6 led to significant IGF-1Ec isoform upregulation in both prostate cancer cell lines (p = 0.0096 and p = 0,001 respectively, students t test, n = 5)." (PMID 30134795, 2018). "GP130, a receptor subunit of IL-6, increased the invasiveness of prostate cancer cells and reduced E-cadherin levels in vitro." (PMID 30558204, 2018). "Several studies have confirmed the relationship between tumor-derived IL-6 and MDSCs in a wide variety of tumor types such as esophageal cancer, prostate cancer, and hepatocellular carcinoma." (PMID 30083161, 2018). "While reports indicate little IL6 production from primary or metastatic clinical prostate cancer samples, the IL6 receptor is present uniformly in a majority of prostate cancers." (PMID 29540470, 2018). "IL-8 affects androgen independence and IL-6 induces androgen receptor activation during prostate cancer cell progression." (PMID 30119678, 2018). "Several lines of evidence have suggested associations between IL6 and CXCL8, and prostate cancer aggressiveness, progression, and poor clinical outcome." (PMID 30473726, 2018). "CRPC patients have elevated serum IL6 levels when compared to patients with untreated hormone‐naïve (HN) prostate cancer." (PMID 29540470, 2018). "The impact of IL‐6 on CSCs on other prostate cancer cell lines in our panel was measured by FACS, where the fraction of CSCs was measured based on triple‐marker‐positive status (CD44+/CD133+/EpCAM+)." (PMID 29741809, 2018).
prostate carcinoma (continued). "The JAK–STAT axis transduces signals of interleukin-6 (IL-6) and interferons (IFNs), mediates antiviral responses, and is frequently altered in prostate cancer (PCa) cells." (PMID 29441069, 2018). "In prostate cancer, tumor cells released IL-6 leading to fibroblasts activation, and in turn, fibroblasts, through MMPs secretion, elicited an EMT phenotype in cancer cells, as well as enhancement of tumor growth and development of spontaneous metastases." (PMID 30227608, 2018). "This compound exerted significant apoptotic activity in PC-3 prostate cancer cells at 100 μM, while it inhibited NF-κB phosphorylation and IL-6 secretion at a concentration range of 10−6–10−4 M." (PMID 29113106, 2017). "Some studies have reported that the addition of exogenous IL-6 to the culture media of prostate cancer LNCaP cells resulted in a dose-dependent growth inhibition with neuroendocrine differentiation, whereas in other instances, cell proliferation was increased." (PMID 28292326, 2017). "In the current study, we not only demonstrated that IL-6 is an oncogene for prostate cancer, but also present a valuable model that recapitulates the role of inflammation in prostate cancer development." (PMID 28077171, 2017). "For instance, IL-6 has been shown to facilitate prostate cancer progression to androgen-independent disease and potentially to promote bone metastasis and neuroendocrine differentiation (NED)." (PMID 28077171, 2017). "IL-6 protects prostate cancer cells against apoptosis through activation of signal transducer and activator of transcription 3 (STAT3) and phosphatidylinositol-3 kinase (PI3K)." (PMID 28292326, 2017). "Most of pro-tumorigenic evidence of IL-6 in prostate cancer was achieved from experiments of oncogene-immortalized cell lines or clinical correlation studies." (PMID 28077171, 2017). "Overall, the preponderance of evidence suggests that IL-6 level is elevated in men with prostate cancer and is related to the clinical outcome of prostate cancer." (PMID 28292326, 2017). "Recent reports indicate that increased constitutive and IL-6-induced STAT3 activation is common in prostate cancer cell lines and tissues." (PMID 27458171, 2017). "The almost complete abolition of the IL-6 response following partial knockdown of miR-21 suggests that PCAT29 expression is very sensitive to changes in miR-21 levels in prostate cancer cells." (PMID 28467474, 2017). "Studies suggest that IL-6 is produced not only by prostate cancer epithelial cells but also by stromal cells, and is elevated in patients with metastatic prostate cancer and seems to mediate survival." (PMID 28558037, 2017). "In this study, we demonstrated that transient ectopic AR-V7 overexpression in LNCaP and 22Rv1 prostate cancer cells activate NF-κB with a resultant increase in IL-6 gene expression." (PMID 28561752, 2017). "This can be related to the fact that prostatic cancer tissue secretes cytokine IL-6 in great quantities and that PBMCs were under normal conditions." (PMID 28356100, 2017). "IL-6 is produced by inflammatory cells and osteoblasts and has ample opportunities to interact with prostate cancer cells." (PMID 28292326, 2017). "IL-6 plays a crucial role in the differentiation of human prostate carcinoma and benign prostatic hyperplasia." (PMID 28467474, 2017). "In particular, the IL-6/STAT3 signaling pathway appears to be crucial for the progression of prostate cancer." (PMID 28467474, 2017). "Elevation of serum levels of IL-6 or activation of IL-6 signaling pathways in the tumor tissue correlates with the shortened overall survival and time to progression in prostate cancer." (PMID 28077171, 2017). "Body fat is known to produce Interleukin-6 (IL-6), tumour necrosis factor-α (TNFα), leptin, and adiponectin, which have been shown to influence prostate cancer progression." (PMID 28680067, 2017).